PDCD1 (programmed cell death 1)
Diseases named in the same sentence as PDCD1 in open-access papers (continued):
Sharing a sentence is not in itself a finding about the gene and the disease.
melanoma (continued). "One study demonstrated the feasibility of CRISPR-edited PDCD1 in effect-memory CTLs with melanoma antigen specificity, and clearly demonstrated its superiority in delaying the growth of PD-L1-positive melanoma." (PMID 35300341, 2022). "Inhibition of LSD1 stimulates antitumor immunity and enhances antitumor efficacy of programmed cell death 1/PD-L1 (PD-1/PD-L1) blocker in breast cancer and melanoma." (PMID 35296335, 2022). "Compared to PD-1− B16-F10 cells or activated WT T-cells, Pdcd1 levels were > 19- or 6-fold enriched (p < 0.01) among PD-1+ melanoma cell fractions or T-cell isolates, respectively." (PMID 35864188, 2022). "Conversely, the CM T-cell data obtained from a previously published melanoma single-cell dataset that we downloaded, the expression of PDCD1 and CTLA-4 was higher than that of TNFRSF9." (PMID 35894206, 2022). "The effects of anti-programmed cell death 1 therapy in mouse models of melanoma have been shown to be enhanced by alkalization through bicarbonate consumption." (PMID 36185175, 2022). "In the current report, we describe an analysis of efficacy and safety in CheckMate 067 at 6.5 years of follow-up, which is the longest follow-up of a phase III trial with an anti-programmed cell death 1–based treatment in melanoma." (PMID 34818112, 2022). "Programmed cell death-1 (PD-1) is an immune checkpoint receptor that promotes melanoma tumor initiation and progression, as well as leading to inhibition of CD8+ T cells’ anti-tumor function." (PMID 36034849, 2022). "Immune checkpoint inhibitors (ICI) targeting programmed cell death 1 (PD-1) have significantly improved the survival outcome of melanoma." (PMID 34268602, 2022). "Pembrolizumab, a monoclonal antibody targeting programmed cell death 1, improves the survival of patients with advanced melanoma." (PMID 33418936, 2021). "An independent study also found PDCD1 to be a poor marker for cells in patient blood with TCRs matching to those in paired melanoma samples." (PMID 33651880, 2021). "With respect to cancer type, the IFX group had a higher proportion of melanoma (47% vs 16%, p<0.001) and less frequent use of programmed cell death 1 protein/ligand one inhibitors (43% vs 61%, p=0.041)." (PMID 34789551, 2021). "Gopalakrishnan and collaborators reported in 2018, the modulation of the response to anti-programmed cell death 1 protein (PD-1) immunotherapy in melanoma patients." (PMID 34950603, 2021). "In melanoma, we have recently shown that FTO promotes the mRNA stability of the melanoma-promoting genes PDCD1, CXCR4, and SOX1013." (PMID 33846348, 2021). "Nivolumab is a programmed cell death 1 (PD-1) antibody that has achieved clinical success in improving recurrence-free survival in a variety of cancers including melanoma, hepatocellular carcinoma, non-small cell lung cancer and head and neck cancers." (PMID 35049864, 2021). "Based on these observations nivolumab, a fully humanized anti-PDCD1 antibody, was developed and approved for treatment, initially for malignant melanoma." (PMID 34067485, 2021). "Monoclonal antibodies targeting the immune regulatory checkpoint receptors of anti-programmed cell death 1 (PD-1) and anti-cytotoxic T-lymphocyte-associated protein-4 (CTLA-4) have significantly improved the prognosis of patients with advanced melanoma." (PMID 34885249, 2021). "In the case of melanoma, for example, tumor-intrinsic PDCD1 expression exhibits an oncogenic effect, whereas in lung cancer the blockade of tumor-intrinsic PDCD1 expression promoted proliferation." (PMID 34067485, 2021). "Later, the use of antibodies against the programmed cell death 1 protein (PD1) further improved the survival of melanoma patients." (PMID 33313405, 2020). "This strategy was applied to analyze the single-cell transcriptome profiles of CD8+ T cells derived from melanoma, which revealed the localized distribution of PDCD1-high cells in the tSNE plot." (PMID 32111241, 2020).
melanoma (continued). "We observed that the TFs are differentially expressed in the PDCD1-high and PDCD1-low subsets among the melanoma or NSCLC samples." (PMID 32111241, 2020). "In both mouse and human melanoma tumors we observed that Tcf7+ Pdcd1+ Tpe were enriched in Slamf6 and depleted of Havcr2 and Entpd1, which encode Slamf6, Tim3, and CD39 cell surface proteins, respectively." (PMID 32174925, 2020). "In melanoma patients receiving either anti-programmed cell death-1 (PD-1) or cytotoxic T-lymphocyte antigen-4 (CTLA-4) therapies, the development of vitiligo-like lesions has been associated with a complete or partial response." (PMID 32707930, 2020). "A total of 199 consecutive patients with head and neck cancer, malignant melanoma, oral cavity cancer, urological cancer, and gastrointestinal cancer who received anti–programmed cell death 1 (PD-1) antibody monotherapy were included." (PMID 33180128, 2020). "The distribution patterns of TOX-high cells and PDCD1-high cells were similar in the latent space of the tSNE plot for both melanoma and NSCLC, which were similar to the distribution patterns of IC genes." (PMID 32111241, 2020). "For further experiments, we focused on the TRBV3-1 T cell clones that included both wild-type and PD-1KO T cell clones to evaluate the functional consequences of PDCD1 editing in melanoma-specific T cell clones." (PMID 32001504, 2020). "Here we demonstrated the feasibility to edit PDCD1 gene in human effector memory melanoma-specific T lymphocytes." (PMID 32001504, 2020). "The anti-programmed cell death 1 (PD-1) receptor antibody represents the second breakthrough in immune checkpoint blockade therapy of melanoma after the approval of ipilimumab." (PMID 32516130, 2020). "Here we showed the efficiency of PDCD1 editing in melanoma-specific CTL produced according to a procedure currently used in a clinical trial in metastatic melanoma patients (MELSORT trial, NCT02424916)." (PMID 32001504, 2020). "Here we show the genetic and phenotypic changes induced by treatment with programmed cell death-1 (PD-1) blockade in a genetically engineered mouse model of melanoma driven by oncogenic BRAF." (PMID 32051401, 2020). "m6A modification of the melanoma cell-intrinsic PD-1 (PDCD1) gene leads to increased mRNA decay via YTHDF2." (PMID 31239444, 2019). "Blockade of tumor immune evasion with programmed cell death 1(PD-1) inhibitors has yielded significant success in therapy for melanoma and a wide variety of other tumors." (PMID 31533865, 2019). "To understand how tumors escape anti-tumor immunity, we investigated tumor-associated T-cell repertoires of patients with advanced melanoma and after blockade of the cytotoxic T-lymphocyte-associated protein 4 (CTLA4) or programmed cell death 1 (PD-1)." (PMID 31275310, 2019). "Consistently we found that IFNγ downregulates FTO in melanoma cells, and FTO mediates resistance to melanoma cell killing by IFNγ through its m6A demethylase activity and downstream targets PD-1 (PDCD-1), CXCR4, and SOX10." (PMID 31239444, 2019). "Immune checkpoint protein inhibitors, such antibodies against PD-L1 (aka CD274) and PD-1 (aka PDCD1), have shown effectiveness against a large number of cancer types, including melanoma, non-small-cell lung cancer, and renal cancer." (PMID 30951669, 2019). "Nivolumab, an anti-programmed cell death-1 monoclonal antibody, has improved the survival of patients with malignant melanoma." (PMID 29884162, 2018). "For example, anti-programmed cell death-1 (PD-1) monotherapy with pembrolizumab has shown intracranial response rates of 20–30% in patients with melanoma or non-small cell lung cancer (NSCLC) brain metastases." (PMID 30319977, 2018). "Programmed cell death-ligand 1 (PD-L1), which is a ligand of programmed cell death-1 (PD-1), is a type I transmembrane glycoprotein that is expressed on antigen-presenting cells and several tumor cells, including melanoma and lung cancer cells." (PMID 29556567, 2018).
melanoma (continued). "Antibodies against programmed cell death-1 (PD-1) have considerably changed the treatment for melanoma." (PMID 29273790, 2017). "The recent advent of inhibitors of immune-checkpoints [cytotoxic T-lymphocyte antigen 4 (CTLA-4) and programmed cell death-1 (PD-1)], and of novel targeted therapies drastically improved survival expectations for advanced melanoma patients." (PMID 29108362, 2017). "In particular, blocking antibodies for PD-1 (PDCD1) or its ligand PD-L1 (CD274) were shown to have clinical efficacy in the treatment of melanoma and lung cancer." (PMID 28474673, 2017). "To test these associations in different tumor types, we selected three T/NK cell modules (FLT3LG.mod, PDCD1.mod and FOXP3.mod that were associated with patient survival (in melanoma, head and neck and bladder tumors, respectively)." (PMID 26398410, 2015). "Initial phase I trials with anti PDCD1 or anti-PD-L1 mAbs have shown considerable promise, with response rates of 18–28% and 10–17%, respectively, in patients with advanced pre-treated melanoma, non-small cell lung cancer (NSCLC), and renal cell carcinoma." (PMID 26562534, 2015). "Inhibition of programmed cell death-1 (PD-1) and its primary ligand, PD-L1, has recently been shown to have efficacy in a number of cancers, including melanoma." (PMID 24693430, 2014). "However, PDCD1 was significantly overexpressed in melanoma samples (2.42-fold increase; p < 0.01), consistent across both quantification methods." (PMID 40869918, 2025). "The observed overexpression of PDCD1 in melanoma patients contributes to the understanding of the complex and multifactorial nature of melanoma, although no significant clinical associations with the analyzed genetic variants were identified in this study." (PMID 40869918, 2025). "In this study, we evaluated if the combination of anti-MIF and anti–programmed cell death 1 (anti–PD-1) therapies could synergistically reduce tumor progression in the immune-responsive YUMMER1.7 melanoma and the MC38 colorectal carcinoma murine models." (PMID 41122966, 2025). "Notably, germ-free mice receiving faecal transplants from responding melanoma patients undergoing anti–programmed cell death 1 protein (PD-1) immunotherapy showed enhanced systemic and antitumour immunity." (PMID 39634265, 2024). "BRD9 could potentially serve as a novel biomarker for diagnosing different cancer types, especially could accurately forecast the prognosis of melanoma patients receiving anti‐programmed cell death 1 immunotherapy." (PMID 38303608, 2024). "Circadian Pdcd-1 mRNA expression was found in tumor-associated macrophage (TAMs), whilst PD-1-positive TAMs count also displayed a significant circadian rhythm in B16/BL6 melanoma transplanted into C57BL/6J mice." (PMID 38834742, 2024). "Additionally, the AUC for KIF20A in predicting response to PD-1 inhibitors was higher than for CD274 and PDCD1, a finding confirmed in another cohort of 28 melanoma patients undergoing anti-PD-1 checkpoint inhibition therapy." (PMID 39555078, 2024). "Moreover, a clinical trial proved the antitumor activity of programmed cell death ligand 1/programmed cell death 1(PD-L1/PD-1) signaling blocking in advanced melanoma." (PMID 36793711, 2023). "Anti-PDCD1 (PD-1) therapy is a well-established immunotherapy approach for melanoma." (PMID 37716991, 2023). "Immune checkpoint inhibitors (ICIs) targeting programmed cell death-1 (PD-1) or its ligand (PD-L1) have achieved significant improvements in clinical adjuvant therapy for esophageal/esophagogastric junction carcinoma, bladder cancer, melanoma, and lung cancer." (PMID 36353552, 2022). "Similarly, another clinical trial in this field reported that FMT in combination with anti-PDCD1 in patients with PDCD1 refractory melanoma was well tolerated and accompanied by clinical benefits in about half of these patients." (PMID 35463305, 2022).
melanoma (continued). "In addition, the MyD88/IL1 receptor (IL1R) axis upregulates programmed cell death (PD)-1 expression on tumor-associated macrophages (TAMs) via promoting recruitment of NF-κB to the Pdcd1 promoter, which sustains their immunosuppressive function in melanoma." (PMID 35309296, 2022). "Medicines that target the programmed cell death 1 (PD-1)–programmed death-ligand 1 pathway, also known as immune checkpoint inhibitors, have dramatically changed the treatment of various types of cancers, including melanoma." (PMID 35044489, 2022). "As reported based on the univariate generalized estimating equation model for programmed cell death 1 inhibitor-related pneumonitis, non-small cell lung cancer is related to a significantly higher incidence of pneumonitis than melanoma for all-grade pneumonitis (4.1% vs. 1.6%; p = 0.002)." (PMID 35578210, 2022). "Anti-programmed cell death 1 (anti-PD-1) or programmed death-ligand 1 (PD-L1) blocking antibodies have shown objective responses in a variety of solid tumors, including melanoma, lung cancer, prostate cancer, breast cancer, ovarian cancer, head and neck cancer, and a subset of colorectal cancers." (PMID 35681659, 2022). "CD274, also known as PD-L1, can bind to PDCD1 to downregulate T cell function in melanoma." (PMID 36704353, 2022). "In addition, FTO suppression increased the m6A methylation of critical pro-tumorigenic melanoma cell-intrinsic genes (programmed cell death-1, PD-1; C-X-C motif chemokine receptor 4, CXCR4; and sex-determining region Y-box 10, SOX10)." (PMID 35628623, 2022). "Sample data of liver cancer, melanoma, lung cancer and pancreatic cancer were downloaded from TCGA database, which were grouped into high and low expression on the basis of mean value of PD-1 (PDCD1) level." (PMID 34326692, 2021). "Programmed cell death-1 (PD-1), programmed cell death-1 ligand (PD-L1), and cytotoxic T-lymphocyte-associated antigen 4 (CTLA-4) therapies are effective in some patients with melanoma or non-small-cell lung cancer." (PMID 34917077, 2021). "Anti- Programmed cell death 1 (PD-1) or programmed death-ligand 1 (PD-L1) blocking antibodies have shown objective responses in a variety of solid tumors including melanoma, lung cancer, prostate cancer, breast cancer, ovarian cancer, head and neck cancer, and a subset of colorectal cancers." (PMID 34790123, 2021). "The multiple therapeutic antibodies that block immune checkpoints, such as cytotoxic programmed cell death protein 1 (PD1, PDCD1) and T lymphocyte associated antigen 4 (CTLA4), showed great effects in treating non-small-cell lung cancer, kidney cancer, and melanoma." (PMID 33917399, 2021). "Importantly, TGFβ-associated pathways emerged as relevant signaling in patients who were non responsive to anti–programmed cell death-1 (PD-1) therapy in both melanoma and metastatic urothelial cancer." (PMID 33499083, 2021). "FTO, prompted by metabolic stress and starvation through the NF-κB signaling pathway and autophagy, increases melanoma growth and decreases response to anti-PD-1 blockade immunotherapy by protecting tumor cell-intrinsic genes (PD-1 (PDCD1), CXCR4 and SOX10) mRNA from decaying." (PMID 34526985, 2021). "Immune checkpoint inhibitors, including monoclonal antibodies targeting cytotoxic T lymphocyte-associated antigen 4 (CTLA4), programmed cell death 1 (PD1), or PD1 ligand (PD-L1), are effective in the treatment of various types of cancer, especially melanoma and lung cancer." (PMID 34944392, 2021). "Melanoma and breast cancer both demonstrated that high expression of CD274 was significantly associated with patient survival and showed largely the same pattern for PDCD1." (PMID 34067485, 2021). "Indeed, treatment with anti-Cytotoxic T-Lymphocyte Antigen 4 and anti-Programmed cell Death 1 have dramatically changed the prognosis of melanoma patients." (PMID 33117345, 2020).
melanoma (continued). "However, among Pdcd1+ Tim3– Slamf6+ cells we found heterogeneous expression of Entpd1, a marker of Tex, both in murine and human melanoma tumors." (PMID 32174925, 2020). "Moreover, CD8+ tumor-infiltrating lymphocytes expressing PDCD1 (encoding PD-1) and Cytotoxic T-Lymphocyte Antigen 4 (CTLA-4) correlate with response to checkpoint blockade therapy and survival in melanoma patients." (PMID 32054102, 2020). "Here a total of 160 patients with advanced melanoma or non-small-cell lung cancer (NSCLC), treated with anti-cytotoxic T-lymphocyte-associated protein 4 (anti-CTLA-4) or anti-programmed cell death 1 (anti-PD-1), were divided into five discovery and cross-validation cohorts." (PMID 33427690, 2020). "Interestingly, they also demonstrated that blocking LDHA in tumor cells improves the efficacy of anti-programmed cell death-1 (PD-1) therapy in melanoma." (PMID 31737570, 2019). "Some results have shown that blocking the programmed cell death-1 (PD-1)/programmed cell death-Ligand 1 (PD-L1) pathway in melanoma with brain metastasis may achieve a clinical cure through the roles of antibodies." (PMID 31729963, 2019). "Durable responses and improved survival rates with programmed cell death-1 (PD-1)-inhibitors have been observed in malignant melanoma, non-small-cell lung cancer (NSCLC), renal cell carcinoma and bladder cancer, changing the therapeutic field in these cancer types significantly." (PMID 29861865, 2018). "Monoclonal antibodies that block immune checkpoint proteins, as anti- programmed cell death-1 (PD-1) and PD-Ligand-1 (PD-L1), thus enhancing the anti-tumor immune response, have demonstrated remarkable efficacy against multiple cancers, including melanoma." (PMID 29165358, 2017). "Additionally, murine model studies have confirmed PDCD1 expression in melanoma cells." (PMID 40869918, 2025). "Single or combination immune checkpoint inhibitors, such as anti-cytotoxic T-lymphocyte associated protein 4 (CTLA-4) and anti-programmed cell death 1 (PD-1), associated with stereotactic RT showed remarkable and durable responses in patients with BM from melanoma without severe side effects." (PMID 38893165, 2024). "Research showed that probiotics could strengthen the efficacy of Immune checkpoint inhibitors such as programmed cell death 1 (PD-1) /programmed cell death ligand 1 (PD-L1) with Bifidobacterium strengthening the efficacy of anit-PD-1/PD-L1 on melanoma-bearing mice." (PMID 38699473, 2024). "Therefore, activated anti-tumor immunity, high PDCD1, CD274, and CTLA-4 expression, and enhanced tumor immunogenicity might explain why the low-risk melanoma patients were found to be more likely to benefit from ICI treatment than the high-risk patients." (PMID 37620409, 2023). "Immune checkpoints that target the programmed cell death-1 (PD-1), programmed cell death ligand-1 (PD-L1), and cytotoxic T-lymphocyte-associated antigen-4 (CTLA-4) have received approval across a wide range of cancer types, including lung cancer, melanoma, and head and neck, among others." (PMID 35565373, 2022). "Additionally, a study of responders and non‐responders with melanoma receiving anti‐programmed cell death 1 protein (PD‐1) immunotherapy revealed both differentially abundant bacterial taxa and different functionality profiles between the groups based on metagenomics and pathway analysis." (PMID 34767683, 2022). "This was accompanied by the expression of proliferation marker Mki67 and exhaustion markers Pdcd1, Lag3, and Tim3 at the RNA level, which is consistent with reports of cell differentiation from naive cells, through a transitional state, toward dysfunction in human melanoma." (PMID 32433953, 2020). "We developed a targeted MS platform to quantify programmed cell death-1 (PD-1), programmed cell death 1 ligand 1 (PD-L1), and programmed cell death 1 ligand 2 (PD-L2) at fmol/microgram protein levels in formalin fixed, paraffin-embedded sections from 22 human melanomas." (PMID 28546465, 2017).